SLIT2 (slit guidance ligand 2)
Diseases named in the same sentence as SLIT2 in open-access papers (continued):
Sharing a sentence is not in itself a finding about the gene and the disease.
tumor (continued). "Moreover Cox multivariate analysis revealed that alterations of SLIT2 and ROBO1 coupled with advanced tumor stage (III/IV), multiparity (≥5) and early sexual debut (<19 years) were predictors of poor prognosis for CACX patients." (PMID 22719878, 2012). "Importantly the expression of the SLIT2 and ROBO1 tumour suppressor genes was also enhanced by GRsiRNA transfection (P<0.05)." (PMID 22132142, 2011). "Moreover, Fisher's pairwise comparison analyses revealed that ROBO1, SLIT2 and ROBO4 significantly discriminated between different histopathological subgroups both in terms of differentiation status and/or tumor staging." (PMID 19114000, 2008). "In tumours without SLIT2 methylation, CASP8 and RASSF1A promoter methylation was detected in 39% (nine out of 23) and 70% (16 out of 23), respectively." (PMID 14735202, 2004). "Interestingly, tumour cells expressing Robo1-FL exhibited apoptosis when SLIT2 was lacking in the microenvironment." (PMID 36792623, 2023). "Importantly, this aberrant tumor angiogenesis prevents the delivery of therapeutic agents and its mechanisms remain incompletely understood, although proangiogenic signaling molecules, including VEGF-A, angiopoietins and SLIT2 are known to be involved." (PMID 37314567, 2023). "We next analyzed two independent SCLC patient cohorts to control for patient and tumor heterogeneity which, respectively, contained seven normal tissues and 79 SCLC tissues, and 24 adjacent normal and SCLC tissues, and found diminished Slit2 levels in SCLC tumors." (PMID 35838343, 2023). "This implies that TGF-β/Smads may not be the only signaling pathway that is involved in Slit2/Robo1-mediated tumor metastasis in CRC." (PMID 31242633, 2019). "However, information on the effects of Slit2 in non-neuronal systems is not well-studied, with recent studies indicating that Slit2/Robo1 complex regulates lung and kidney development, tumor angiogenesis and metastasis." (PMID 23294842, 2013). "Furthermore, we demonstrated in vitro growth suppression when SLIT2 was expressed in tumour cell lines that had no endogenous SLIT2 expression due to methylation." (PMID 15534609, 2004). "To examine whether the expression and activation of Slit2 and Robo1 are correlated with intestinal tumorigenesis, we first analyzed the protein expression of Slit2 and Robo1 in the tumor tissues relative to their matched surrounding non-cancerous colonic tissues by immunohistochemical analysis." (PMID 25605242, 2015). "We performed IHC to analyze the expression and localization of SLIT1, SLIT2, and ROBO2 proteins in human PCa and non-neoplastic samples adjacent to the tumor." (PMID 40508075, 2025). "Further in vivo experiments illustrated that in the absence of SLIT2, ROBO1 significantly reduced the tumour burden induced by SW-1990 cells in subcutaneous PDAC xenograft mice." (PMID 36792623, 2023). "In this front, we wanted to investigate the clinical relevance of the SLIT2 and SLIT3 promoter methylation in metachronous metastasis positive and negative tumor specimens of CRC patients." (PMID 27462788, 2016). "In contrast, methylation levels of SLIT2, MAL and IGFBP7 in tumor samples were higher when compared with levels in matched non-malignant lung tissues (P<0.0001, P=0.0010 and P<0.0001, respectively)." (PMID 23381221, 2013). "To investigate the relationships between SLIT2 promoter methylation and de novo methylation of RASSF1A and CASP8, we compared the frequencies of CASP8 and RASSF1A methylation in tumours with and without SLIT2 methylation." (PMID 14735202, 2004). "By immunohistochemistry, we have revealed a significant increase in the expression of β-catenin and two known downstream targets of Wnt/β-catenin pathway cyclin D1 (CCND1) and Axin2 in the tumor tissues of the ApcMin/+;Slit2 and DMH/DSS-Slit2 mice, as opposed to their respective controls." (PMID 25605242, 2015).
tumor (continued). "In WT mice, ROBO1-FL-expressing tumour cells displayed a predominant population in liver metastatic niches, especially in Kpc1199Mix-I-modelled cells, during coadaptation with hepatocytes, while in Slit2/CKO mice, Kpc1199CTRL cells outcompeted Kpc1199Robo1-FL cells in the absence of SLIT2." (PMID 36792623, 2023).
cancer (100 papers, 2004 to 2026). A tumor composed of atypical neoplastic, often pleomorphic cells that invade other tissues. "On the other hand, the extracellular-matrix-secreted glycoprotein SLIT2 has been linked to neuronal development, myogenesis, leukocyte chemotaxis, and cancer." (PMID 39596804, 2024). "Expression of SLIT2 or ROBO1 is frequently decreased in different types of cancer, due to promoter hypermethylation or loss of heterozygosity." (PMID 36942388, 2023). "The association between SLIT2 downregulation and patient’s prognosis has been reported in different types of cancer." (PMID 35053460, 2022). "In turn, loss of SLIT2 reactivates the developmental program of branching, leading to invasive cancer." (PMID 28440283, 2017). "MiR-218, is encoded by an intron of the SLIT2 tumor suppressor gene, is known to be associated with the development and progression of several cancers." (PMID 23320911, 2013). "Downregulation of miR-218 in cancer cells has been shown to be caused by promoter hypermethylation of SLIT2 and SLIT3 genes." (PMID 23483249, 2013). "The downregulation of miR-218 in cancer cell was caused by promoter hypermethylation of SLIT2 and SLIT3 genes." (PMID 23159910, 2012). "Slit protein binds to the roundabout receptor and acts as a midline repellent to guide axonal development during embryogenesis In humans, three SLIT orthologues have been identified, but to date only SLIT2 has been implicated in cancer." (PMID 14735202, 2004). "For instance, the Slit2/Robo1 axis has been linked to cancer proliferation via the Warburg effect in osteosarcoma, and it induces epithelial–mesenchymal transition (EMT) in colorectal epithelial cells by associating Src and E-cadherin with the Robo1 cytoplasmic domain." (PMID 41227302, 2025). "In addition, even fibroblast-derived SLIT2 also exerts opposite effects in different types of cancer, and this phenomenon is probably associated with the biological heterogeneity and versatility of CAFs." (PMID 37443302, 2023). "Loss of Slit2/3 upregulates Cxcl12 in mammary epithelium and the surrounding stroma, as well as Cxcr4 in the mammary epithelium, suggesting inhibitory roles of SLITs in cancer progression." (PMID 36942388, 2023). "The findings presented herein reveal the associations between CAFs and cancer cells through SLIT2/ROBO1 and inflammatory signaling, and the key molecules involved may serve as potential biomarkers and therapeutic targets for GC." (PMID 37443302, 2023). "Slit2 exerts antitumor effects in various cancers; however, the underlying mechanism, especially its role in regulating the immune, especially in the bone marrow niche, system is still unknown." (PMID 34777365, 2021). "The approach of our work paves the way to predict if mutations in ROBO1/4 and SLIT2 have the potential to disrupt their cognate physical interaction that in turn, could regulate the crucial hallmarks of cancer viz." (PMID 33318575, 2020). "Here, we report that the intratumoral microenvironment is a mediator of PDA-associated neural remodeling (PANR), and we highlight factors such as ‘SLIT2' (an axon guidance molecule), which is expressed by cancer-associated fibroblasts (CAFs), that impact on neuroplastic changes in human PDA." (PMID 25590802, 2015). "Recent studies also noted that endothelium-secreted SLIT2 promotes innervation and cancer cell migration in mouse models of metastatic breast cancer." (PMID 40777309, 2025). "The identification of inhibitory molecules such as SLIT2 offers novel targets for comprehending and addressing neuronal invasion in cancer." (PMID 40092993, 2025). "Research indicates that the axon-guidance molecule SLIT2 functions as an inhibitor of neural invasion in cancer." (PMID 40092993, 2025). "Recently, Slit2/Robo signaling has garnered attention in cancer research, particularly regarding cell proliferation, migration, and angiogenesis." (PMID 41227302, 2025).
cancer (continued). "Conversely, blocking the interaction between SLIT2 and its receptor roundabout guidance receptor 1 (ROBO1) enhances the motility and invasiveness of PDAC cells, further supporting the inhibitory effects of SLIT2 on cancer cell migration and invasion." (PMID 39119085, 2024). "The results indicated that the gene expression of ADAM12, FLRT2, and SLIT2 was higher in ER alpha-positive cancers." (PMID 39596804, 2024). "Together, our results show that knockdown of SLIT2 reverses the cancer-suppressive effects induced by inhibition of miR-423-5p." (PMID 38902704, 2024). "Together, these findings elucidate a central role of chemorepellent SLIT2 in the regulation of mTORC1 activity with important implications for innate immunity and cancer cell survival." (PMID 37311584, 2023). "The kinase domain directly interacts with ROBO1, a process that is enhanced by SLIT2 stimulation, and it also increases the activities of inflammatory signaling and cytoskeleton remodeling, which is a key step in cancer metastasis." (PMID 37443302, 2023). "Together, these findings suggest that SLIT2, a canonical neurorepellent, is a key regulator of autophagy and organelle homeostasis in innate immune and cancer cells." (PMID 37311584, 2023). "SLIT2 is an evolutionarily conserved secreted glycoprotein which regulates directed cell migration (chemotaxis) of multiple cell types, from leukocytes to cancer cells." (PMID 37311584, 2023). "We further show that attenuation of auto/para-crine SLIT2/ROBO1 signaling in cancer cells results in hyperactivation of mTORC1 and diminished autophagic flux." (PMID 37311584, 2023). "In spite of the recent advances, the mechanisms responsible for SLIT2’s diverse actions on innate immunity and cancer remain poorly understood so far." (PMID 37311584, 2023). "Some of the significant cancer hallmark terms are epithelial-mesenchymal transition (MSX1, CXCL12, SCG2, SLIT2), KRAS signaling up (F13A1, ADAMDEC1), inflammatory response (CCL5, VIP), IL-6/JAK/STAT3 signaling (CXCL13)." (PMID 35486660, 2022). "In these cancer cells, (a) the Slit2 gene promoter is hypermethylated to suppress its expression, and (b) ROBO expression is downregulated through increased ubiquitin-mediated degradation." (PMID 36361532, 2022). "Very recently, it was shown that disseminated cancer cells secrete RNA to trigger Slit2 secretion, which promotes cancer cell migration, intravasation and metastasis." (PMID 34073394, 2021). "Further elucidation of mechanisms by which SLIT2/ROBO1 signaling simultaneously inhibits cancer cell migration and macropinocytosis will be important for potential development of new oncologic therapies." (PMID 32807784, 2020). "SLIT2, a member of neuronal guidance cues, has been reported to regulate inflammation and cancer progression." (PMID 32760720, 2020). "In neuronal cells, the cancer-related gene SLIT2 was found to be upregulated, as were six other cancer-related genes (PDGFRA, DDR2, RSPO3, IL6ST, NTRK2, and HEY1) in cardiomyocytes and one cancer-related gene (HSD3B1) in hepatocyte-like cells." (PMID 32127560, 2020). "We also provide evidence that SLIT2 can attenuate the growth of KRAS-transformed cancer cells by inhibiting macropinocytosis." (PMID 32807784, 2020). "All cancer-associated missense variants of ROBO1/4 and SLIT2 from COSMIC were screened for their pathogenicity." (PMID 33318575, 2020). "Previous reports have shown that Slit2 plays important roles in various cancers, and the regulatory function of Slit2 is different in different cancers." (PMID 31242633, 2019). "To investigate the role of Slit‐Robo family in GC, we first measured Slit2, 3 and Robo1, 2, 3 expression in 54 paired cancer tissues and matched adjacent non‐cancer tissues from GC patients." (PMID 30896071, 2019). "The promoter’s hypermethylation often leads to Slit2 down-regulation in most types of cancers, including CRC." (PMID 31242633, 2019).
cancer (continued). "Thoroughly understanding the biological roles of Slit2-WT and Slit2-ΔE15 in cancer and in an immune response would be helpful for developing therapeutic strategies for inhibiting cancer cell growth and metastasis that do not compromise the immune system." (PMID 30717252, 2019). "Mechanistically, the SLIT2/ROBO1 axis exerted cancer-promoting effects on OS via activation of the SRC/ERK/c-MYC/PFKFB2 pathway." (PMID 29523788, 2018). "USP33 deubiquitinates and thus maintains the stability of ROBO1, thereby regulating the activity of SLIT2 and inhibiting cancer cell metastasis." (PMID 29743814, 2018). "Deletions or epigenetic modifications in the genes for Slit2 and Robo1 have been ascertained in numerous cancer types." (PMID 29864155, 2018). "SLIT2/ROBO1 is a conserved ligand-receptor system that is involved in cancer cell proliferation, apoptosis, migration, and angiogenesis in a cell-type dependent manner." (PMID 29523788, 2018). "High cancer cell expression of Robo1 correlates with increased survival, while low fibroblast Slit2 expression correlates with lymph node involvement." (PMID 26828520, 2016). "Previous studies have showed that Slit2-Robo1 pathway was frequently inactivated in human cancers, including CRC." (PMID 27923383, 2016). "These target genes include E-Cadherin, TIMP-3, and Slit2, which are responsible for cancer cell proliferation and invasion." (PMID 26484567, 2015). "Down-regulation of Slit2 has been reported in several other cancers, including those from lung, breast, cervix, skin and ovary." (PMID 25605242, 2015). "Notably, LT1-3’s action is Robo-independent, potentially circumventing the conflicting roles of full-length Slit2 in cancer cells’ Slit/Robo signaling." (PMID 41227302, 2025). "In PDAC, SLIT2 is expressed by cancer cells and CAFs and can regulate innervation and metastasis." (PMID 40777309, 2025). "On the whole, these findings revealed the connections of CAFs and cancer cells through SLIT2/ROBO1 and inflammatory signaling, and the key molecules involved in this process may serve as potential biomarkers and therapeutic targets for GC." (PMID 37443302, 2023). "In cancer cells, SLIT2 negatively regulates mTORC1 signaling to control cell growth." (PMID 37311584, 2023). "However, methylation levels of SLIT2 gene were significantly higher in plasma cell-free DNA of 72 NSCLC patients than in that of 61 cancer-free patients (p = 0.001, Wilcoxon rank sum test)." (PMID 35053460, 2022). "However, when the recombinant Slit2 protein is added to cancer cells, Slit2 activates the expression of USP33, a deubiquitinating enzyme, which prevents ROBO from degradation and stabilizes the protein." (PMID 36361532, 2022). "Tavora et al23 reported that TLR3 could induce the expression of SLIT2 and promote cancer progression." (PMID 33783985, 2021). "Interestingly, ECs can also release angiocrine factors such as Slit2, which inhibit cancer cell proliferation and motility." (PMID 34073394, 2021). "Besides LIF and TGFβ, there are some key regulatory molecules such as CXCL12 and SLIT2 in the model which are cancer progression and prevention players, respectively." (PMID 32384110, 2020). "To test the hypothesis that SLIT2 could inhibit macropinocytosis in cancer cells, we chose two KRAS-transformed adenocarcinoma cell lines, PANC-1 and DLD-1." (PMID 32807784, 2020). "SLIT2 promotes angiogenesis, and the migration of specific cancer cells." (PMID 32760720, 2020). "The expression of Slit2 is repressed by hypermethylation in many cancers." (PMID 30717252, 2019). "However, the molecular mechanisms of Slit2/Robo1 signaling in the regulation of tumorigenesis and cancer progression of CRC still require further exploration." (PMID 31242633, 2019).
cancer (continued). "Slit2 is frequently inactivated in human cancers including lung cancer, breast cancer, colorectal cancer, ovarian cancer, glioma and HCC and its tumor suppressive role that inhibits cancer cell invasion and migration, angiogenesis and growth, has been well-studied." (PMID 29859044, 2018). "Moreover, studies have shown that USP33-mediated SLIT2/ROBO1 signalling participates in the development of cancer." (PMID 29743814, 2018). "The mechanisms by which Slit2 promotes intestinal tumorigenesis and cancer progression are unclear." (PMID 25605242, 2015). "Slit2 was expressed in adjacent epithelial cells and also in stromal cancer cells." (PMID 24597571, 2014). "However, the role of Slit2 in cancer is highly context‐dependent." (PMID 35838343, 2023). "Interestingly, restoring Slit2 expression decreases metastatization and neural invasion by reducing chemoattraction between Schwann cells and cancer cells, thus indicating that acting on Slit2 and Robo 1 signaling might prevent PNI." (PMID 31248001, 2019). "During development, the SLIT2 protein functions as a secreted chemorepellent so that restoration of SLIT2 function by reversal of epigenetic inactivation or administration of SLIT2 agonists might provide novel therapeutic opportunities for human cancers." (PMID 14735202, 2004). "Cell-surface proteases, such as ADAM12, VNN1, and FLRT2, would cleave ECM components with the aid of SLIT2, CYR61, and ADAM12 in response to mechanical stimuli, allowing for cancer cells to migrate more easily." (PMID 39596804, 2024). "In the sample of patient B19, four cancer related genes CCR7, AKT1, SLIT2 and CDK6 were found with HPV integrations before treatment, and none was found after treatment." (PMID 37914994, 2023). "Our group recently demonstrated that Slit guidance ligand 2 (SLIT2) is an endogenous inhibitor of macropinocytosis in macrophages and cancer cells." (PMID 37311584, 2023). "This escape from repellent SLIT2/ROBO signaling helps SCs migrate to cancer cells and contributes to the mutual chemical attraction between cancer and nerves." (PMID 35186076, 2022). "The endothelial-derived SLIT2 protein, together with its receptor ROBO1, drove cancer cells to migrate and infiltrate into endothelial tissue." (PMID 34007851, 2021). "They corresponded to cell fate determination, cell cycle activation, epigenetic modifications, DNA damage response, as well as cancer-related pathways including Wnt/β-catenin, PI3K/AKT/mTOR, Slit2/Robo1, MYC, and ErbB2-ErbB3 axes." (PMID 33747361, 2021). "The SLIT2/ROBO pathway has both beneficial and harmful effects on the growth of malignant tumor cells." (PMID 32420368, 2020). "The promoter hypermethylation of SLIT2 and SLIT3 genes results in the down‐regulation of miR‐218 expression in cancer cells." (PMID 33107676, 2020). "The BAMBI (Vanhara and Souček, 2013), LCN2, F13A1, CDKN2A, SLIT2, and CLU were reported to individually play a role in cancer development and progression." (PMID 33585439, 2020). "SLIT2, a secreted glycoprotein of the SLIT family, is involved in the epithelial-mesenchymal transition (EMT) process, which permits cancer cells to acquire migratory, invasive, and stem-like properties." (PMID 32795291, 2020). "Our study reveals the inhibitory function of Slit‐Robo signalling in GC and uncovers a role of USP33 in suppressing cancer cell migration and EMT by enhancing Slit2‐Robo1 signalling." (PMID 30896071, 2019). "Taken together, the findings reveal a previously unappreciated function of SLIT2/ROBO1 signaling in OS, which is intertwined with metabolic alterations that promote cancer progression." (PMID 29523788, 2018). "miR-218 is an intronic miR of SLIT2 and SLIT3, which are epigenetically silenced in different cancer cells and tissues." (PMID 27462788, 2016). "SLIT2 and SLIT3 are commonly found to be silenced by aberrant DNA hypermethylation in promoter regions in cancers." (PMID 26610476, 2015).